KRAS (KRas proto-oncogene, GTPase)
Diseases named in the same sentence as KRAS in open-access papers (continued):
Sharing a sentence is not in itself a finding about the gene and the disease.
ovarian carcinoma (continued). "Regulation of the hnRNPA1 RNA-binding protein by either miR-15a-5p or miR-25-3p leads to increased ovarian cancer growth by inhibiting the generation of miR-18a-3p, an inhibitor of KRAS." (PMID 29389895, 2018). "Collectively, these findings suggest that enhanced inflammation plays a role in the progression of KRAS-induced ovarian cancer." (PMID 27483433, 2016). "Ovarian cancer cell lines HOC-7 and transformed cells were first analysed for mutations in the KRAS gene." (PMID 27484466, 2016). "In order to test if ETV5 is required for the expression of E2F targets in RAS-driven ovarian cancer cells we revisited the HEY cell line, which carries a KRASG12D mutation, as well as gain of the KRAS gene." (PMID 25557169, 2015). "One of the histological and molecular subtypes of ovarian cancer is low-grade serous (LGS) ovarian carcinoma characterized by BRAF, KRAS, NRAS and ERBB2 mutation, amplification or overexpression." (PMID 25408231, 2014). "Additionally, the low frequency of KRAS mutation or BRAF mutations in type II ovarian carcinomas in the current and previous studies suggest that p-ERK expression may be affected by the other receptor tyrosine kinase regulation mechanisms (i.e., EGFR, Her2, etc.)." (PMID 23820584, 2013). "Ovarian carcinomas with KRAS or MAPK1 amplifications are clinically most frequent in type II carcinomas that exhibit aggressive behavior." (PMID 23820584, 2013). "Although mutations in PIK3CA, KRAS, PTEN, BRAF and ARID1A are uncommon in HGSOC, they are characteristic of other ovarian cancer subtypes." (PMID 23839242, 2013). "Larger sample studies are required to definitively establish the percentage of KRAS/MAPK1 amplification on type II ovarian carcinomas." (PMID 23820584, 2013). "Recent genome-wide analysis by TCGA, single nucleotide polymorphism arrays identified KRAS and MAPK1 as two of the most frequently amplified genes in high-grade serous ovarian carcinomas with the prototypic type in type II ovarian carcinomas." (PMID 23820584, 2013). "Other mechanisms able to deregulate KRAS gene in ovarian cancer are gene amplifications that account in about 11% of ovarian tumors and short RNA molecule (miRNA) let-7." (PMID 24063014, 2013). "This difference in sensitivity to the RAS–RAF–MEK–ERK pathway between ovarian cancer and the latter types is intriguing, and it probably reflects organ-specific roles of the KRAS and BRAF oncogenes." (PMID 19018267, 2008). "This difference in prognostic significance between ovarian cancer and the latter types is intriguing, and it probably reflects organ-specific roles of the KRAS/BRAF pathway." (PMID 19018267, 2008). "Therefore, ovarian cancer patients with KRAS or BRAF mutations may benefit from CI-1040 treatment." (PMID 19018267, 2008). "The analysis revealed that the KRAS protein could be utilized as a promising discriminator in the differential diagnosis of ovarian cancer progression characteristics, including progressive stage, lymph node invasion, and metastatic status." (PMID 40913040, 2025). "A significant difference in FK866-sensitivity could be observed between wildtype and KRAS/PI3K-mutant ovarian cancer cells (P = 0.0355 and P = 0.0379, respectively)." (PMID 41419662, 2025). "The negative associations of KRAS mutations with recurrence and survival are not limited to mOC and are evident in other subtypes of epithelial ovarian cancers as well." (PMID 40896434, 2025).
ovarian carcinoma (continued). "The opposite situation was observed for women bearing ovarian cancer with mutations in KRAS and/or BRAF who had better prognosis than those without them." (PMID 38391958, 2024). "Both Grisham and Moujaber reported that for high-grade ovarian cancer, there is a loss rather than a gain of the BRAF and/or KRAS mutations, while low-grade ovarian cancers are predominantly characterized by these mutations." (PMID 38391958, 2024). "For example, enhanced tumour growth correlated with increased AMPK and fatty acid oxidation in ovarian cancer cells, linked to dysregulation of mTORC1 expression in renal cell carcinoma and has been connected to the hypoxia and oncogenic HRAS or KRAS pathways in glioblastoma and bladder cancer." (PMID 37697969, 2023). "While it rarely contains KRAS mutations, it shows RAS pathway activation in about 25% of tumors and KRAS amplification in 13.9% of patients, especially in HGSOC patients, who represent the prototypical type II ovarian cancer." (PMID 36142803, 2022). "Intriguingly, KRAS amplification was found in 13.2% of type II ovarian cancer tissue samples and might represent an essential factor in the growth and resistance of HGSOC." (PMID 36142803, 2022). "In conclusion, we suggest that KRAS, NOXA, PUMA, c-FOS, and c-JUN may be associated with poor prognosis in ovarian cancer." (PMID 35807169, 2022). "Interestingly, the mutation rates for commonly reported genes in ovarian cancer such as RB1, PTEN, PIK3CA, NRAS, KRAS, and BRAF were below 3% in the entire cohort." (PMID 33016563, 2021). "Histologic types of ovarian cancer have been associated with different genetic alternations and both KRAS and BRAF mutations have been found in low-grade serous ovarian cancer (LGSOC), 16 to 44% KRAS mutation and 2 to 20% BRAF mutation." (PMID 33801965, 2021). "Gains of chromosome 12 (containing the KRAS oncogene), increased with age in ovarian cancer." (PMID 33879792, 2021). "let-7 suppresses multiple ovarian cancer oncogenes including KRAS, HRAS, c-MYC, and HMGA-2." (PMID 32256980, 2020). "Finally, our findings suggest that KRASG12D/K104A regulates GEF to activate KRAS signaling and promote cell growth, invasion and migration in lung and ovarian cancer cell lines." (PMID 33060649, 2020). "Based on the studies in lung and ovarian cancer, we hypothesise that KRAS activation influences histological phenotype and is associated with a mucinous phenotype in GC." (PMID 31111275, 2019). "Defactinib, a small-molecule and well-tolerated FAK inhibitor, has been evaluated in phase I/Ib study combined with paclitaxel in patients with relapsed ovarian cancer (NCT01778803), and in a phase II study in patients with the NSCLC KRAS mutation (NCT01951690)." (PMID 31212816, 2019). "Studies examining endometriotic lesions and ovarian cancer from the same patient have shown concordant mutations in ARID1A, phosphatase and tensin homolog (PTEN), PIK3CA, and KRAS, suggesting that mutations in endometriosis cause a predisposition to ovarian cancer." (PMID 30087267, 2018).
ovarian carcinoma (continued). "Ovarian carcinomas with KRAS mutation showed frequent lack of NBS1 detection (p = 0.013, Fisher’s exact test) and a trend for MRE11 negativity (p = 0.08, Fisher’s exact test)." (PMID 28073364, 2017). "Remarkably, Buparlisib was efficient almost exclusively in ovarian cancer, the exception being a PR observed in a KRAS mutated non-small cell lung Cancer patient." (PMID 28008141, 2017). "KRAS in particular markedly promoted ovarian cancer progression." (PMID 27483433, 2016). "c-MYC and KRAS were transduced into the mouse ovarian cancer cell line ID8." (PMID 27483433, 2016). "VEGF concentrations in ascites significantly increased in c-MYC-induced ovarian cancer, whereas the concentrations of inflammatory cytokines in ascites were significantly high in KRAS-induced ovarian cancer and were accompanied by an increased number of neutrophils in ascites." (PMID 27483433, 2016). "Mutations in KRAS and BRAF, which may activate the mTOR/PI3K/AKT pathway, are common in low-grade ovarian cancers (60 %) but rare in high-grade cancers." (PMID 24848881, 2014). "First, differences in histological heterogeneity in type II ovarian carcinoma, including high-grade serous, high-grade endometriod, and carcinosarcoma used to assess amplification KRAS/MAPK1 may produce significant variability among results." (PMID 23820584, 2013). "In addition, we compared phenotypes in cultured type II ovarian carcinoma cell lines with various KRAS or MAPK1 copy numbers after treatment using a selective MEK inhibitor." (PMID 23820584, 2013). "The KRAS-variant was significantly enriched in uninformative (BRCA negative) double primary patients, being found in 39% of patients accrued within two years of their ovarian cancer diagnosis." (PMID 22662244, 2012). "This, as yet, has not been explored with anti-EGFR therapy in ovarian cancers although the KRAS pathway is implicated in ovarian tumorigenesis particularly in low grade serous and mucinous carcinomas." (PMID 24281034, 2010). "KRAS and BRAF mutations are less common in high grade ovarian cancers." (PMID 19638206, 2009). "It has been shown that EGFR mutations do not play a role in ovarian cancer, while KRAS mutations are very well documented." (PMID 19358724, 2009). "Several studies have shown that RAS mutations (specifically at KRAS codon 12) are prevalent in ovarian cancers of mucinous histology but not in tumors of non-mucinous histologies." (PMID 18761742, 2008). "Furthermore, they suggest that the CI-1040-induced phenotypes depend on the mutational status of KRAS and BRAF in ovarian cancers." (PMID 19018267, 2008). "We employed complementary approaches-CRISPR/Cas9 gene editing, Tet-ON inducible knockdown, polypurine reverse Hoogsteen hairpin (PPRH) oligonucleotides, and the pan-KRAS inhibitor BI2865-to investigate whether KRAS modulation enhances chemotherapeutic efficacy in ovarian cancer models." (PMID 41683990, 2026). "KRAS has been shown to be amplified in ovarian endometrioid carcinoma and HGSOC and has been associated with an aggressive phenotype of metastatic uterine endometrioid carcinoma, whereas MYC amplifications have been observed in a variety of ovarian cancers, including endometrioid carcinomas." (PMID 40981433, 2025). "Therefore, downregulation of HMGA2 and KRAS by let-7d could exert an anti-oncogenic effect in ovarian cancer." (PMID 34298978, 2021). "Hence, expressions of key regulators AKT1, KRAS, EPCAM and CD44 can be correlated to increasing or decreasing the risk of disease progression, so, they can be potential prognostics markers or drug targets in ovarian cancer." (PMID 31752757, 2019).
ovarian carcinoma (continued). "Besides the mutations, copy number amplification the gene can also be observed in around 20% of the testicular germ cell tumors (TGCTs) and ovarian cancers (OVs), which may also confer the tumor cells to a KRAS gain-of-function shift in the cellular phenotype." (PMID 30406144, 2018). "Similarly, the oncogene KRAS plays an important role in ovarian cancer." (PMID 30509235, 2018). "Moreover, mutations in KRAS and BRAF, which may activate the mTOR/PI3K/AKT pathway, are common in low-grade ovarian cancers (60%)." (PMID 26075229, 2015). "Interestingly, 11 percent of ovarian cancers display KRAS amplification (copy number 4 or greater) and these tumors largely do not have KRAS mutation." (PMID 24874471, 2014). "Furthermore, type II ovarian carcinomas with KRAS or MAPK1 amplification may be sensitive to a potential targeted therapeutic agent." (PMID 23820584, 2013). "Interestingly, the co-existence of KRAS mutation and PIK3CA mutation has also been found in other tumor types such as ovarian carcinoma, suggesting that such co-occurrence might provide a selective advantage to carcinoma cells from various origins." (PMID 23785428, 2013). "Interestingly, whilst in preclinical models mutations in KRAS have been found to confer resistance to PI3K pathway inhibition in this trial 2/7 ovarian cancer patients with coexisting PIK3CA and KRAS or BRAF mutations responded to the anti-PI3K pathway treatment." (PMID 22970424, 2012). "Therefore, detection of KRAS and BRAF mutations in ovarian cancers may identify patients who will benefit from CI-1040 therapy." (PMID 19018267, 2008). "In conclusion, the current study revealed the oncogenic ability of the KRAS gene through promoting tumor growth and the tumor suppressor function of the NOXA gene through its apoptotic characteristics in ovarian cancer development and progression." (PMID 40913040, 2025). "The differential expression of KRAS and NOXA genes holds promise as potential biomarkers for ovarian cancer development and progression." (PMID 40913040, 2025). "The serum concentrations of KRAS and NOXA were analyzed in both healthy individuals and patients with ovarian cancer." (PMID 40913040, 2025). "The correlation between the protein levels of KRAS and NOXA with tumor aggressiveness features has been assessed to explore their impact on ovarian cancer progression." (PMID 40913040, 2025). "Otherwise, KRAS, ERBB2, and RHOA are all in connection with ovarian cancer, but little is known about the mechanisms involved in other ovarian functional regulation of these genes, and there are also only a few exosomal miRNA-related pieces of research." (PMID 38037065, 2023). "Our results shed new light on the critical role of PLK1 in reversing PARPi resistance in KRAS-amplified HGSOC, and offer a new therapeutic strategy for this class of ovarian cancer patients where only limited options currently exist." (PMID 36142803, 2022). "Rahman and colleagues revealed that the gene amplification of KRAS and MAPK1 was essential for type II ovarian carcinomas' growth." (PMID 36276992, 2022). "KRAS and IGF1 are the top activated signaling, along with WNT1 inhibited, in immunotherapy responded ovarian cancer." (PMID 34921236, 2021). "While the direct targeting of KRAS is challenging, encouraging results have been reported with the MEK1/2 inhibitor trametinib in low-grade serous ovarian cancer, an uncommon epithelial ovarian cancer subtype." (PMID 32485873, 2020).
ovarian carcinoma (continued). "Conversely, KRAS-wild-type CRC (SW48, HT29), prostate cancer (PC-3), ovarian cancer (COV362) cell lines and a normal colon cell line (CCD841CoN) were resistant to vitamin C when used both as a single agent and in combination with STS." (PMID 32393788, 2020). "We used ID8, a murine ovarian cancer cell line, and ID8-KRAS, an oncogenic KRAS (G12 V)-transduced ID8 cell line in this study." (PMID 30509235, 2018). "Among the molecular markers, HER2, KRAS, BRCA1, BRAF, and EGFR were independent and statistically significant prognostic factors for ovarian cancer patient outcomes." (PMID 26490766, 2015). "Our model supported notion that the four molecules in the EGFR/HER2/KRAS/BRAF signaling pathway also produce the synergic effect, exerting their own effect on ovarian cancer progression." (PMID 26490766, 2015). "Previous studies have demonstrated the efficacy of MAPK and PI3K inhibitors in KRAS- and PI3K-driven mouse models of lung and ovarian cancer." (PMID 25431423, 2015). "Using fluorescence in situ hybridization, immunohistochemistry, and retrospectively collected clinical data, KRAS and MAPK1 amplifications were identified in 9 (13.2%) and 5 (7.4%) of 68 type II ovarian carcinoma tissue samples, respectively." (PMID 23820584, 2013). "miR-193a induced the inhibition of DNA synthesis and apoptosis by targeting genes including ARHGAP19, CCND1, ERBB4, KRAS, MCL1, indicating a tumor suppressive role of this miRNA in epithelial ovarian cancer cells." (PMID 23588298, 2013). "In ovarian cancer, ATMIN promotes cisplatin resistance by regulating the DYNLL1-MRN signaling axis; in tongue cancer, ATMIN promotes tumor metastasis by activating KRAS pathway, while its role in NPC remains to be investigated." (PMID 38321024, 2024). "Aberrations in KRAS and BRAF contribute to dysregulated cellular processes in ovarian cancer." (PMID 37958970, 2023). "In summary, we provided evidence that KRAS, NOXA, PUMA, c-FOS, and c-JUN could be promising biomarkers in ovarian cancer." (PMID 35807169, 2022). "However, a few recent ovarian cancer case reports indicate their potential as biomarkers for MEK inhibitors, and encouraging preclinical data are available for KRAS inhibitors." (PMID 33947352, 2021). "AZD compounds did not change the mRNA expression of BRCA1/BRCA in ovarian cancer cells, but AZD8835 inhibited BRCA1/BRCA2 mRNA expression and p-ERK protein expression in OVCAR-8 cells with the KRAS mutation." (PMID 32194423, 2020). "In ovarian cancer network, out of seventy leading hubs in the ovarian cancer network, we could able to explore five such KRs which are AKT1, CD44, MCAM, KRAS and EPCAM." (PMID 31752757, 2019). "Following the definition of key regulators, we could able to identify five KRs, namely, AKT1, KRAS, EPCAM, CD44 and MCAM, that are key regulators (organizers) of the ovarian cancer network." (PMID 31752757, 2019). "A study including 140 patients (breast, cervical, endometrial, and ovarian cancers) from phase I program treated with PI3K/AKT/mTOR inhibitors, measured different potential biomarkers (PIK3CA, KRAS, NRAS, and BRAF) to see if a correlation was possible with the response rate of patients." (PMID 28008141, 2017).